CD4 (CD4 molecule)
Diseases named in the same sentence as CD4 in open-access papers (continued):
Sharing a sentence is not in itself a finding about the gene and the disease.
Immunodeficiency (continued). "LncRNA analysis provides compelling evidence to explain the plasticity of CD4+ T-cell development from a molecular perspective, which aids in the discovery of new therapeutic targets for immune diseases." (PMID 35794862, 2022). "Studies of miR-142-5p in CD4+ T cells are related to cancer or immune diseases such as multiple sclerosis." (PMID 35428200, 2022). "HIV-infected persons were ART-naïve, however persons with CD4 counts < 400 cells/mm3 were excluded in order to study the impact of HIV infection prior to severe immunodeficiency." (PMID 34276702, 2021). "The development of NHLs was also related to immunodeficiency, but second to KS, which median CD4 count was 117/μL (BL 241/μL, DLBCL 94/μL, other NHLs 13/μL, respectively)." (PMID 34934097, 2021). "Baseline TTV plasma concentrations and CD4+ cell count are predictive for the course of immune recovery in HIV-1-infected patients with severe immunodeficiency." (PMID 33537915, 2021). "None of the enrolled patients at enrollment had severe immunodeficiency (e.g., CD4 < 200 cells/mm3, or CD4 < 15%) or showed physical signs of such immunodeficiency, and all were on antiretroviral therapy." (PMID 34835262, 2021). "Conversely, in the case of immunodeficiency, a pro-inflammatory response including Th1 CD4, cytotoxic CD8, NK cells, and IFNγ release seems beneficial for M1 macrophage activation, despite the impact of inflammation on lung tissue." (PMID 34436164, 2021). "PjP occurs predominantly in people living with HIV (PLWH) with marked immunodeficiency with CD4 positive lymphocytes in peripheral blood (CD4 count) of less than 200 cells/μL, or less than 14 % of total lymphocytes." (PMID 34118121, 2021). "The criteria used to define immunodeficiency accounted only for CD4+ T cell counts and was based on cut off points based on previous literature and commonly used in clinical practice." (PMID 34845263, 2021). "The 33-year-old patient of East-Asian origin exhibited late onset combined immunodeficiency characterised by recurrent chest infections, panhypogammaglobulinemia and CD4+ T cell lymphopenia." (PMID 34908525, 2021). "The severe reduction in CD4+ T cells can account for most of the immunodeficiency late in HIV infection." (PMID 34696319, 2021). "CD4 helper T-cell depletion for long periods leads to “on-target, off-tumor” toxicities and immunodeficiency in patients." (PMID 34162832, 2021). "In this regard, the median CD4+ lymphocyte count at diagnosis is 63–165 cells/μL, indicating a status of important immunodeficiency." (PMID 34771697, 2021). "CD4+ T TILs recruitment in tumors often follows a regulatory T cell (Treg) subset, which leads to severe immunodeficiency and can be produced by TAMs through cytokine expression, as reported in ovarian cancer patients." (PMID 34089486, 2021). "The number of CD4 T-cells in both patients was close to 200 per microliter of blood, suggesting the progression of immunodeficiency and possible reactivation of infection in seropositive patient." (PMID 34959511, 2021). "This immunodeficiency is attributed to the impairment of CD4+-mediated viral killing, and is reversed by antiretroviral protease inhibitor." (PMID 34591866, 2021). "The Dolutegravir group had higher baseline CD4+ levels and higher CD4+ levels at six months, suggesting minor immune dysfunction at baseline." (PMID 34784398, 2021). "IL-6 can differentiate naïve CD4+ αβT cells into Th17 cells which contributed to the pathophysiologic process of immune disorders." (PMID 33902534, 2021). "Low nadir CD4 T-cell counts in HIV+ patients are associated with high morbidity and mortality and lasting immune dysfunction, even after antiretroviral therapy (ART)." (PMID 34938286, 2021). "In aging and immune disorders, increased aberrant CD4+CD28null occurs, with predominantly NKG2D expression." (PMID 33808849, 2021).
Immunodeficiency (continued). "The CD4+ T cells was significantly lower in the O-KS group than in the other two groups, and 8 of 9 individuals in the O-KS group had advanced immunodeficiency with a CD4+ T cell count <200 cells/μL." (PMID 31951641, 2020). "The AMC trial was difficult to interpret, given the unusual dosing of rituximab, use of obsolete antiretroviral combinations, and inclusion of patients with severe immunodeficiency (with CD4+ cell counts <50/mm3)." (PMID 32794362, 2020). "This underscoring the multiple regulatory capacities of the MO p-miR pool, since immunodeficiency in HIV cART-naïve individuals is largely due to apoptosis of CD4 T cells and to the chronic activation of the immune system." (PMID 33643043, 2020). "In terms of the immunologic status on initiating ART, 30.2% (n = 254) of all participants initiated treatment with severe immunodeficiency (CD4 <200 and/or manifestations of opportunistic disease)." (PMID 32986730, 2020). "Of note, severe immune deficiency at switch to second‐line ART was close to 60% in the rest of SSA as compared to 26% in Southern Africa, where 100% of clinic sites had routine CD4 and VL monitoring." (PMID 32297485, 2020). "The pattern of immunodeficiency in classical A-T is typical of aging, with lymphopenia affecting CD4+ and CD8+ T-cells and B cells." (PMID 33362793, 2020). "Eighty-three (68,5%) children had moderate-to-severe immune deficiency at thetime of ART initiation: young children (1-5 y) and older children (>5-10 y)had higher CD4+ T-cell count %, 18.3% and 19.1%, respectively, thanadolescents (>10-19 y), 14.4%." (PMID 33111912, 2020). "A novel mechanism of DC-dependent CD4+ T cell immune dysfunction was attributed to IL-6 overproduction." (PMID 32542025, 2020). "Our results support that well-treated PWH have residual immune dysfunctions since a positive HIV status was independently associated with having elevated proportions of CD8+ immune activation, CD4+ senescence, and CD4+ and CD8+ apoptosis." (PMID 33117394, 2020). "Previous studies have also shown that CD4+ T cells can engage in crosstalk with the gut flora to participate in immune diseases during inflammation." (PMID 33584283, 2020). "The reduction of lymphocytes will lead to immune disorders, for example, the reduction of CD4+ T cells and the disorder of CD4+/CD8+ ratio are all related to rapid tumor growth and lymph node infiltration of cervical cancer." (PMID 32477958, 2020). "A previous study showed that CXCR4 was upregulated in naive CD4+ and CD8+ T cells and CD4+ central memory T cells, which have a crucial role in modulating immune dysfunction." (PMID 32983229, 2020). "Similar to other ADs, HT is often accompanied by immune dysfunction, especially imbalanced subsets of CD4+ T-helper cells." (PMID 33029083, 2020). "As such, we believe this technology can greatly benefit the field of MHC-II antigen prediction, and therefore the study and application of CD4+ T cell recognition across pathogen infection, cancer, and immune disorders." (PMID 32887877, 2020). "Neuromeningeal cryptococcosis is an opportunistic infection caused by a ubiquitous environmental encapsulated yeast (Cryptococcus species), usually seen in patients with HIV infection and advanced immunodeficiency (CD4 count < 100 cells/μl)." (PMID 30867046, 2019). "Kaposi’s sarcoma is another opportunistic disease associated with severe immunodeficiency, mostly occurring in individuals with HIV infection and a CD4 count < 100 μl, even though it can be seen at any stage of the disease." (PMID 30867046, 2019). "According to CD4 T lymphocytes, mild thrombocytopenia was 33.33% (17/51) among those with severe immunodeficiency, with a statistically significant difference (p = 0.003) as compared to those with higher CD4." (PMID 31554515, 2019). "More than half (55.4%) of the participants were at WHO clinical stage I or II, and 124 (29.0%) had a CD4 count below the threshold for severe immunodeficiency at ART initiation." (PMID 31319659, 2019).
Immunodeficiency (continued). "The severity of immunodeficiency, such as CD4 depletion in HIV infection, also affects the MBC response to PCV, as it has been shown that HIV+ patients with CD4 count <400/μL had lower MBC numbers than those with CD4 >400/μL one month post-PCV13." (PMID 30700048, 2019). "Severe immunodeficiency (a decline in CD4 T lymphocytes below 200/μL of blood) was recorded in three persons, and in one patient the number was close to this level (216/μL of blood)." (PMID 31690039, 2019). "LAM has diagnostic value for identifying TB in HIV-positive patients with signs and symptoms of TB and advanced immunodeficiency, including those with a CD4 count of 100–199 cells/μl." (PMID 31039161, 2019). "Stress and menstrual cycle are known influencers of immune parameters, including natural killer cells and CD4+:CD8+ ratio, and it is possible OLE has an improving effect on URI risk in women, ameliorating menstrual immune dysfunction." (PMID 30744092, 2019). "The specificity with which Salp15 binds to CD4+ T cells, and the inhibition of CD4+ T cell activation and proliferation are very promising properties for the treatment of immune diseases." (PMID 31998324, 2019). "CD4+CD25+FOXP3+ nTreg cells derived from thymus are known to modulate immune disorders such as autoimmunity, allergy, and graft rejection by suppressing activation of naïve T cells, effector T cells and memory CD4+ and CD8+ T cells." (PMID 31815635, 2019). "In the same setting, CD8 counts often rise, leading to inverted CD4/CD8 ratios that are an independent measure of immune dysfunction." (PMID 31555284, 2019). "The study marks the first occasion when peptides containing immunodominant epitopes for CD4+ T cells in an organ-specific immune disease have been shown to stimulate rapid systemic cytokine release in patients." (PMID 31457091, 2019). "CD4 cell count and CD4% at the start of cART and the percentage of children starting cART with severe immunodeficiency by country income group." (PMID 30614622, 2018). "Further, impaired IFN-γ production and reduced CD4+ and CD8+ T cell response was observed in ICOS-deficient patients leading to immunodeficiency and autoimmunity." (PMID 29892278, 2018). "Overall, participants had advanced immunodeficiency, with median CD4 counts of 168 cells/mm3 (Q1, Q3; 86, 232) and log HIV viral load of 5.1cps/ml (Q1, Q3: 4.6, 5.6)." (PMID 29385208, 2018). "More than two thirds (70.0%) of the children had CD4 counts below the threshold for severe immunodeficiency." (PMID 29482600, 2018). "In this study, most of the HIV-infected patients with PTB presented with severe immunodeficiency (CD4+ T cell count < 50 /mm3)." (PMID 29587840, 2018). "The pathogenesis of HIV immunodeficiency is mainly dependent on the cytopatic effects exerted by the virus against infected CD4+ T cells." (PMID 30459765, 2018). "Animal models have shown that lymphocytes T CD4+ facilitate clearance of B. burgdorferi and immunodeficiency leads to higher spirochete burdens and higher infectivity of these bacteria." (PMID 29776392, 2018). "In response to immune system disorders induced by various antigens, including viral or bacterial pathogens, naïve CD4+ T cells can differentiate into distinct effector T helper cell lineages capable of differentially regulating the immune response." (PMID 30429675, 2018). "The change of CD4+/CD8+ ratio is considered as one of the important markers of human immune dysfunction." (PMID 30296293, 2018). "Owing to this observation and the known critical role of CD4+ T cells in sepsis immune dysfunction, we chose to further interrogate the phenotypes and function of CD4+ T cells in this system." (PMID 29338031, 2018). "CD4/CD8 ratio have been pointed as a more accurate marker of immune dysfunction than absolute CD4+ T cell count." (PMID 30541557, 2018).
Immunodeficiency (continued). "The literature is conflicting regarding the use of CD4/CD8 ratio as a surrogate marker to describe immune dysfunction and to predict the progression towards NAEs and mortality." (PMID 30261902, 2018). "WHO recommendations suggest that the LF-LAM test has greatest utility in hospital inpatients with signs and symptoms of TB and advanced immunodeficiency (CD4 T-cell count < 100 cells/mm3)." (PMID 28774293, 2017). "Later, it was shown that suppressing HIV replication with antiretroviral therapy (ART) rapidly increased peripheral blood CD4+ T-cell counts and reversed immunodeficiency." (PMID 28588579, 2017). "The very low median CD4 counts at HIV-1/TB diagnosis highlights that most patients were diagnosed with advanced immunodeficiency." (PMID 28558689, 2017). "Immunodeficiency was typically advanced and overall median CD4 cell counts were lower among those who were ART-naive compared to those currently receiving ART (115 cells/μL versus 212 cells/μL; P < 0.001)." (PMID 28320384, 2017). "Among patients, 12 had HIV related immunodeficiency, when it was reported, CD4 cell counts was always <150/mm3." (PMID 28476105, 2017). "These patients were predominantly women (n = 249; 61%) with advanced immunodeficiency (median CD4 count, 150 cells/uL) and anaemia (median haemoglobin, 9.6 g/dL)." (PMID 28883510, 2017). "TB-HIV co-infection represents a lethal combination: the immunodeficiency induced by HIV leads to progression of TB disease and TB itself decreases the CD4 count and worsens the immunodeficiency caused by HIV in children." (PMID 28236807, 2017). "During the initiation of ART, 59 (24.0%) of study participant were found to be in advanced immunodeficiency state with CD4 <200 cells/mm3 and of these, 8 (3.3%) were at severe immunological stage with CD4 count <50 cells/mm3." (PMID 28596843, 2017). "HIV infection is characterized by severe immunodeficiency, a consequence of numerical and functional CD4+ T cell depletion." (PMID 28421130, 2017). "Apoptosis of uninfected cells is a key element of HIV pathogenesis and is believed to be the driving force behind the selective depletion of CD4+ T cells leading to immunodeficiency." (PMID 27577111, 2017). "Paradoxically, the baseline levels of cytokines observed in these patients cannot control the infection due to advanced immunodeficiency, as corroborated by the low CD4 counts and low CSF white cell counts observed." (PMID 28486489, 2017). "Cryptococcus neoformans was isolated in one HIV-infected child with severe immunodeficiency i.e. an absolute CD4 count of < 20 × 109/L and a CD4 percentage of < 1%." (PMID 29207958, 2017). "Due to the specificity of Salp15 for CD4 and its capacity to inhibit the activation of CD4 T cells, the use of this tick saliva protein has been suggested for the treatment of immune diseases." (PMID 28878331, 2017). "The CD4+ T cell count has been used as a surrogate for the level of immune dysfunction that exists in patients with HIV infection." (PMID 29230423, 2017). "Other studies have shown that despite effective cART and CD4+ recovery above 500 cells/μl, a persistently low CD4:CD8 ratio acts as a marker of continuing immune dysfunction, and the onset of HIV-related diseases." (PMID 28743248, 2017). "We have shown that sarcoidosis CD4+ T cells derived from the periphery exhibit immune dysfunction when compared to healthy control cells (, –4)." (PMID 29234685, 2017). "As T-cell responses have pivotal roles in human immune diseases, inhibition of ASM bioactivity blocks CD4+ T-cell signaling, and dampens pathogenic Th responses." (PMID 28749465, 2017). "Only 1 mother had a recent CD4 count, precluding inferences about the impact of varying degrees of immunodeficiency." (PMID 27838668, 2016). "This is particularly true as HIV-infected children generally experienced immunodeficiency in such context (i.e. 375 median CD4 cells/mm3 from our findings)." (PMID 27656883, 2016).
Immunodeficiency (continued). "While classic PML presents in patients with <200 CD4+ cells and only in 5% of those with severe immunodeficiency, rare cases of PML in immunocompetent patients with and without underlying disease have been reported." (PMID 27529042, 2016). "Our high proportion of disseminated TB (45 %) is due to the advanced immunodeficiency status of our population, with median CD4 cell counts of 72 cells/mm3, which were lower than previously reported (109 and 112 CD4 cells/mm3)." (PMID 27286652, 2016). "The identification of depression in HIV patients is also important because of itsassociation with more severe immunodeficiency, lower CD4 count, higher viral loads andmore rapid disease progression." (PMID 27626305, 2016). "Increased frequencies of CD4+ T cells with an activated/exhausted phenotype correlate with exacerbated immunodeficiency in aviremic HIV-2-infected individuals." (PMID 27525551, 2016). "Conventionally, infected immature DCs are thought to travel to the lymph node, where they mature to interact with CD4+T cells, transferring the infection and resulting in CD4+ T-cell depletion with accompanying catastrophic immunodeficiency." (PMID 28936255, 2016). "The median percentage of CD4 cells was 20% (IQR: 13.5 to 26.2) and 85% of children had moderate to severe immune deficiency at baseline." (PMID 27015798, 2016). "Advanced immunodeficiency was common (median CD4 count, 133 cells/μL), and approximately one half of patients had previously been treated for TB disease." (PMID 26730391, 2015). "This abnormal immunodeficiency in F9 mice was also evident in the lymph nodes, where a significant reduction in the proportion of single positive CD4 and CD8 T cells was apparent." (PMID 26505904, 2015). "It is important to highlight that the patients evaluated in that study were newly diagnosed with HIV infection, had advanced immunodeficiency (mean CD4 count: 147.1 ± 84 cell/mm3, 70.1% had CD4 count <200 cell/mm3), and were HAART naïve." (PMID 26798547, 2015). "The inverse relationship observed between baseline CD4 count and anti-TPO antibody titers raises the possibility of increased immunodeficiency early in the course of disease being linked to increased occurrence of autoimmunity later." (PMID 26798547, 2015). "Immunodeficiency was typically advanced and CD4 cell counts (median, 149 cells/μL) were lower among those who were ART-naive compared to those currently receiving ART (115 cells/μL versus 212 cells/μL; P <0.001)." (PMID 26275908, 2015). "CD4+ T cells and viral loads are recognised as the primary markers of immunodeficiency in HIV infection." (PMID 26436092, 2015). "This haplotype is clearly linked with the lowest pretreatment plasma viral loads, the highest CD4+ T cell counts at care-entry, as well as with the highest nadir of CD4+ T cell count, and reflects delayed progression to immunodeficiency." (PMID 26068923, 2015). "Advanced immunodeficiency was common; the median CD4 count was 101 cells/uL and more than 80% had stage 3 or 4 disease." (PMID 25889688, 2015). "The 20 patients who died despite receiving a transfusion typically had advanced immunodeficiency (median admission CD4 count, 68 cells/μL) and very severe anemia (median hemoglobin level, 6.0 g/dL)." (PMID 26730391, 2015). "Progression to severe immunodeficiency (CD4 count <350 cells/μL): prognosis based on early CD4:CD8 ratio and other potential factors in 499 HIV-1 seroconverters." (PMID 26191056, 2015). "This need to degrade SAMHD1 during SIV infections of memory CD4+ T cells in vivo selects for Vpx revertant viruses capable of generating high levels of plasma viremia and inducing immunodeficiency." (PMID 25996507, 2015). "This review reconsiders CD4:CD8 ratio in the light of advances in the understanding of immune dysfunction and examines its pathophysiological features and implications on clinical outcome and HIV reservoir size in long-term treated HIV-positive adults." (PMID 26130226, 2015).